ARID3A (AT-rich interaction domain 3A)
Description:
Transcription factor which may be involved in the control of cell cycle progression by the RB1/E2F1 pathway and in B-cell differentiation.
Synonyms: Bright; DRIL1; DRIL3; E2FBP1
Tractability: PROTAC: UniProt records ubiquitination sites on it; ubiquitination databases record sites on it; its protein half-life has been measured.
Gene: Protein-coding gene on chromosome 19 (924,528 to 975,939, forward strand). Ensembl gene ENSG00000116017.
Subcellular location: Nucleus; Cytoplasm
Subcellular location (Human Protein Atlas): Nucleoplasm; Cytosol
Gene Ontology:
Molecular function: protein binding; chromatin binding; DNA binding; identical protein binding; transcription coregulator activity
Biological process: regulation of transcription by RNA polymerase II; positive regulation of transcription by RNA polymerase II
Cellular component: cytosol; membrane raft; nucleoplasm; cytoplasm; nucleus
Genetic constraint (gnomAD): Loss-of-function variants: 11 observed, 41.19 expected, observed/expected ratio (o/e) 0.27, 90% interval 0.17 to 0.44. The synonymous counts are far from expectation, so gnomAD's model fits this gene poorly and the ratio says little. Missense variants: 715 observed, 765.02 expected, observed/expected ratio (o/e) 0.93, 90% interval 0.88 to 0.99. Synonymous variants: 395 observed, 327.43 expected, observed/expected ratio (o/e) 1.21, 90% interval 1.11 to 1.31.
Homologues: Orthologues: chimpanzee ARID3A (99% identical), macaque ARID3A (97% identical), pig ARID3A (88% identical), dog ARID3A (86% identical), guinea pig ARID3A (85% identical), mouse Arid3a (81% identical), rat Arid3a (80% identical), tropical clawed frog arid3a (63% identical), zebrafish arid3a (53% identical), Drosophila melanogaster retn (33% identical), Caenorhabditis elegans cfi-1 (30% identical). Paralogues in human: ARID3B (40% identical), ARID3C (34% identical).
Diseases named in the same sentence as ARID3A in open-access papers:
ARID3A is named in the same sentence as 63 diseases in open-access papers, as found by Europe PMC text mining. Sharing a sentence is not in itself a finding about the gene and the disease. The quoted sentences say what the papers report.
colorectal cancer (7 papers, 2016 to 2024). A primary or metastatic malignant neoplasm that affects the colon or rectum. "As a transcription factor, ARID3A participates in many cellular processes and is reported to promote the progression of tumors such as ovarian cancer, colorectal cancer, and nasopharyngeal cancer." (PMID 34778251, 2021). "ARID3A facilitated the malignant phenotypes through upregulating AURKA in colorectal cancer." (PMID 35125116, 2022). "Apart from SP4, EGR1, ARID3A, and NKX6-1, the remaining transcription factors have been reported in colorectal cancer, which supports the importance of these candidate DEMs in the mechanism of CRC tumor." (PMID 36798788, 2023).
systemic lupus erythematosus (7 papers, 2015 to 2025). An autoimmune multi-organ disease typically associated with vasculopathy and autoantibody production. "The gene signatures for the ARID3a-expressing B cells indicate a strong correlation to IFN, suggesting a potential connection between ARID3a and the lupus-associated cytokine, IFNα." (PMID 31554207, 2019). "Although a number of contributing factors are likely to influence SLE pathology, in this review, we will highlight the molecular and cellular associations of ARID3a with the common lupus pathologies of autoantibody production, interferon induction, and the promotion of clinical nephritis." (PMID 31554207, 2019). "We hypothesized that ARID3a+ naïve B cells would eventually produce autoantibodies, explaining associations between ARID3a expression and disease activity in lupus." (PMID 28580178, 2015). "Therefore, inflammatory events in LDNs associated with ARID3a expression may precede the activation of autoimmune anti-self B cells in lupus." (PMID 31554207, 2019). "Although the defects we observed upon loss of Arid3a may appear subtle, increased ARID3A expression in human B cells correlates with the severity of systemic lupus erythematosus, which may be indicative of a more general function of this transcription factor in autoimmunity." (PMID 29114251, 2017). "Consistent with our findings in mice, we observed that human systemic lupus erythematosus (SLE) patients had expanded numbers of peripheral blood ARID3a+ B cells that were associated with increased disease activity (p = 0.0038)." (PMID 28580178, 2015). "The transcription factor ARID3A plays an important regulatory role in various cancers, renal fibrosis, systemic lupus erythematosus and primary biliary cholangitis, but its role in cardiovascular diseases was rarely reported." (PMID 40913516, 2025). "Examination of a random cross section of 115 lupus patients revealed abnormally high numbers of circulating ARID3a+ B cells (up to 40-fold increases) compared with healthy controls and patients with rheumatoid arthritis." (PMID 31554207, 2019). "Recently, we performed cross-sectional and longitudinal studies of systemic lupus erythematosus (SLE) patients to determine if ARID3a is over-expressed in human autoimmune disease." (PMID 28580178, 2015). "Because ARID3a is over-expressed in lupus pDCs, LDNs, and B cells, we hypothesize that ARID3a contributes to interactions between these three cell types in lupus." (PMID 31554207, 2019). "Indeed, we observed a very strong correlation between ARID3a and IFNα expression in lupus pDCs." (PMID 31554207, 2019). "Moreover, ARID3A expression was upregulated in B cells, and plasmacytoid dendritic cells from patients with systemic lupus erythematosus (SLE) and correlated with disease severity." (PMID 36977669, 2023). "Therefore, we hypothesized that ARID3a+ naïve B cells present in lupus patients, but not in healthy controls, might be precursors of this innate B cell population, and that they would preferentially produce autoreactive immunoglobulins." (PMID 28580178, 2015).
colon cancer (5 papers, 2016 to 2026). "Our results showed that the ARID family was upregulated in colon cancer, with ARID3A being the main component that promoted colon cancer development." (PMID 41605861, 2026). "Specifically, ARID3A enhanced colon cancer cell proliferation, migration, and invasion both in vivo and in vitro." (PMID 41605861, 2026). "In colon cancer, ARID3A, a transcriptional regulator, inhibits AKR1C3 transcription, leading to downregulation of AKR1C3." (PMID 38523637, 2024). "The expression of ARID3A was markedly increased in colon cancer tissue compared with matched normal colonic mucosa." (PMID 27403158, 2016). "In conclusion, ARID3A was a key member of the ARID family in the development of colon cancer." (PMID 41605861, 2026). "This interaction between AKR1C3 and ARID3A was associated with decreased chemosensitivity to 5-fluorouracil (5-FU) in colon cancer cells, suggesting that the ARID3A to AKR1C3 ratio may serve as a valuable marker for predicting the prognosis of colon cancer patients." (PMID 38523637, 2024). "Li Yafei and colleagues identified ARID3A as a transcription factor for AKR1C3, inhibiting its expression in colon cancer cells." (PMID 38523637, 2024). "In colon cancer, AKR1C3 downregulation by ARID3A enhances 5-FU sensitivity." (PMID 41009436, 2025).
breast carcinoma (4 papers, 2019 to 2023). "In addition, it has been shown in a previous study that the complex of Arid3a, Arid3b, and Kdm4c modulates the chromatin configuration of stemness genes for breast cancer by decreasing H3K9me3." (PMID 30616715, 2019). "Based on our results, high mRNA expression of ARID3A was interrelated to poor prognosis in HER2-riched type breast cancer, but a better prognosis in basal-like type breast cancer." (PMID 33592583, 2021). "Date analysis showed ARID3A might take part in the breast cancer regulatory networks, no other deeper research." (PMID 33592583, 2021). "The expression of ARID1A, ARID1B, ARID2, ARID3A, ARID4A, and ARID4B in no-luminal subtypes was lower than luminal subtypes, however, ARID3C, ARID5A, and JARID2 mRNA expression were higher in no-luminal subtypes of breast cancer tissues." (PMID 33592583, 2021).
hepatocellular carcinoma (4 papers, 2022 to 2025). A malignant tumor that arises from hepatocytes. "Furthermore, Xu Wang and his team discovered that the exosomal lncRNA HMMR-AS1 modulates hepatocellular carcinoma (HCC) progression by influencing macrophage polarization via the miR-147a/ARID3A axis in a hypoxic environment." (PMID 40806330, 2025). "The upregulated exosomal lncRNA HMMR-AS1 could boost M2 polarization via the miR-147a/ARID3A axis in hepatocellular carcinoma cells (HCC), thus leading to disease progression and poor prognosis." (PMID 36612282, 2022).
liver cancer (4 papers, 2022 to 2025). An epithelial or non-epithelial malignant neoplasm that arises from the liver. "We also investigated the underlying mechanism by which ARID3A is specifically upregulated in liver cancer." (PMID 36008383, 2022). "The mRNA level of ARID3A was notably upregulated in tumour tissues, and a high ARID3A level was markedly associated with poor overall survival in liver cancer patients." (PMID 36008383, 2022). "However, the molecular mechanisms underlying the oncogenic role of ARID3A in liver cancer remain largely unexplored." (PMID 36008383, 2022). "Taken together, these data suggest that the increased ARID3A expression in liver cancer may be associated with DNA demethylation and open chromatin accessibility at the ARID3A genomic locus." (PMID 36008383, 2022). "ARID3A regulates the viability of liver cancer cells and influences metastasis both in vitro and in vivo." (PMID 36008383, 2022). "Here, we identified AT-rich interacting domain 3A (ARID3A) as one of the most upregulated stemness-related transcription factors in liver cancer by an in vitro functional screen." (PMID 36008383, 2022). "The results showed that KDM3A knockdown strikingly decreased the migration, invasion and tumoursphere formation of ARID3A-overexpressing liver cancer cells." (PMID 36008383, 2022). "Given that ARID3A expression is often increased in liver cancer and is highly related to stem cell characteristics, we first evaluated the effect of ARID3A on the tumoursphere formation capability." (PMID 36008383, 2022). "Collectively, these results provide evidence highlighting a transcription-dependent mechanism of ARID3A in stemness regulation in liver cancer." (PMID 36008383, 2022). "We also evaluated the effect of ARID3A on liver cancer cell growth in vivo." (PMID 36008383, 2022). "ARID3A can promote liver cancer cell viability and metastasis both in vitro and in vivo." (PMID 36008383, 2022). "We performed ATAC-seq in 4 paired liver cancer tissues and matched nontumour tissues to assess open chromatin regions at the ARID3A gene locus and found that a highly accessible chromatin region was located at the third intron region of ARID3A in liver cancer patients." (PMID 36008383, 2022). "Moreover, the results of transwell assays, together with those of wound healing assays, revealed that a higher ARID3A level notably enhanced the migration and invasion capabilities of liver cancer cells." (PMID 36008383, 2022). "ARID3A also can promote the migration, invasion and tumoursphere formation capabilities of c-Myc-transformed HiHep cells, which indicated that ARID3A was involved in liver cancer progression." (PMID 36008383, 2022). "Interestingly, after ARID3A knockdown, the proliferation of liver cancer cells was significantly diminished." (PMID 36008383, 2022). "Furthermore, we determined by Co-IP that endogenous ARID3A can interact with CEP131 in liver cancer cells." (PMID 36008383, 2022). "Furthermore, positive ARID3A expression was found in 45 of the 111 (40.5%) primary liver cancer samples and in 23 of the 123 (18.7%) adjacent NT tissues in cohort III (P = 0.0002)." (PMID 36008383, 2022). "Overexpression of either ARID3A or CEP131-induced KDM3A mRNA expression in liver cancer cells, and this induction was abolished by silencing either CEP131 or ARID3A." (PMID 36008383, 2022). "As demonstrated by their enhancement of tumorigenicity, the liver cancer stemness markers CD326, CD133, CD44, ALDH1A1 and CD13 were found mostly downregulated in ARID3A knockdown cells and upregulated in ARID3A overexpressed cells." (PMID 36008383, 2022). "In the present study, we demonstrated that ARID3A and CEP131 co-occupy the promoter region of KDM3A and contribute to its transcriptional activity, ultimately enhancing liver cancer cell oncogenic ability." (PMID 36008383, 2022). "ARID3A and CEP131 promote an ES cell gene signature through activation of KDM3A and contribute to the poor prognosis of liver cancer patients." (PMID 36008383, 2022).
liver cancer (continued). "Similarly, overexpression of ARID3A strongly promoted the migration and invasion of CLC2 and CLC7 cells derived from Chinese liver cancer patients." (PMID 36008383, 2022). "Similar to the effects of silencing ARID3A expression, silencing the expression of CEP131 reduced the cell migration, invasion and tumoursphere formation capabilities, while overexpression of CEP131 enhanced these capabilities in liver cancer cells." (PMID 36008383, 2022). "Interestingly, ARID3A can regulate the expression of KDM3A, thereby driving the expression of ES signature genes through H3 lysine 9 dimethylation (H3K9me2) in liver cancer cells." (PMID 36008383, 2022). "ARID3A interacts with CEP131 and co-occupies the KDM3A promoter region to activate KDM3A transcription, thereby modulating the expression of ES signature genes in liver cancer cells." (PMID 36008383, 2022). "In liver cancer, integrated analysis of gene expression profiles of HCC led to the construction of a transcriptional regulatory network that contained most downstream DEGs (differentially expressed genes), including ARID3A." (PMID 36008383, 2022). "ARID3A can cooperate with CEP131 to transcriptionally activate KDM3A and promote expression of ES signature genes, suggesting that ARID3A and CEP131 are potential targets for the development of new anticancer therapeutics for liver cancer." (PMID 36008383, 2022). "The ARID3A/CEP131-KDM3A regulatory circuit could serve as a prognostic indicator and potential therapeutic target for liver cancer." (PMID 36008383, 2022). "However, overexpression of ARID3A did not affect the proliferation of liver cancer cells." (PMID 36008383, 2022).
ovarian carcinoma (4 papers, 2015 to 2022). A malignant neoplasm originating from the surface ovarian epithelium. "Arid3a: Transcription factor Arid3a is a paralog of the family of interactive AT-rich domains and is associated with the regulation of genes in the development of B cells and cancer such as ovarian cancer." (PMID 33412518, 2021). "RNA sequencing data revealed the ARID3A/B complex-induced genes involved in cancer and stem cell processes in ovarian cancer cells." (PMID 36008383, 2022).
atherosclerosis (3 papers, 2023 to 2025). A disease characterized by the build-up of fatty material and calcium deposition in the arterial wall resulting in partial or complete occlusion of the arterial lumen. "The eEF1A1/ARID3A/PKC‐δ complex critically regulates macrophage glycolytic reprogramming in atherosclerosis by mediating ARID3A phosphorylation and nuclear translocation, thereby driving ENO2 transcriptional activation." (PMID 39973763, 2025). "Neferine targets eEF1A1 to disrupt the eEF1A1/ARID3A/PKC‐δ complex to inhibit ENO2‐mediated macrophage glycolytic reprogramming in atherosclerosis." (PMID 39973763, 2025).
Autoimmunity (3 papers, 2015 to 2019). The occurrence of an immune reaction against the organism's own cells or tissues. "ARID3a is also expressed in mature B1 and marginal-zone (MZ) B cells, two cell types associated with autoimmunity in several systems." (PMID 31554207, 2019). "Gene expression data from pDCs and LDNs with high levels of ARID3a protein provide new insights into genes associated with autoimmunity and increases in SLEDAI scores." (PMID 31554207, 2019). "Together, these data suggest a role for ARID3a in innate antibody production and autoimmunity." (PMID 28580178, 2015).
Cirrhosis (2 papers, 2022). A chronic disorder of the liver in which liver tissue becomes scarred and is partially replaced by regenerative nodules and fibrotic tissue resulting in loss of liver function. "Several oncogenic transcription factors (TFs) inferred with DoRothEA35 including FOS, ETS2, RELB, SOX10, ERG, WT1 and JUND and TFs supporting stemness such as PBPJ and ARID3A were upregulated in cirrhosis patients and correlated with bacterial translocation." (PMID 35803930, 2022).
head and neck cancer (2 papers, 2020 to 2022). A primary or metastatic malignant neoplasm affecting the head and neck. "Since ARID3A is another component in this complex in head and neck cancer stem cells 36, we also analyzed the association between ARID3A and other molecules in CRC samples." (PMID 32483441, 2020). "The complex composed of ARID3B and ARID3A is directly repressed by Let-7 in head and neck cancer, modulates H3K9me3 at stemness genes, and further regulates cancer stemness." (PMID 36008383, 2022). "We previously demonstrated that in head and neck cancer cells, ARID3B forms a complex with ARID3A." (PMID 32483441, 2020).
lymphoma (2 papers, 2019 to 2024). A malignant (clonal) proliferation of B- lymphocytes or T- lymphocytes which involves the lymph nodes, bone marrow and/or extranodal sites. "Thus, the attenuation of B1a development by Arid3a-deficiency blocked the ability to promote development of B CLL/lymphoma." (PMID 30930899, 2019). "Inhibition of miR-129-5p and the overexpression of ARID3A in lymphoma cells were found to enhance immune escape by upregulating PD-L1 expression, which was under the transcriptional control of ARID3A." (PMID 38462628, 2024). "Enforced expression of Arid3a also augmented the capacity of the TCL1 Tg to promote B CLL/lymphoma, including those expressing the VH12+ aPtC BCR as previously found among the B1a cell-derived B CLL/lymphoma in TCL1 Tg+ mice." (PMID 30930899, 2019). "However, crossed with B1a-restricted VH/D/J IgH knock-in mice allowed to confirm that SLC-unassociated B1a cell increase and CLL/lymphoma generation can occur in aged from Arid3a increased adult BM." (PMID 30930899, 2019). "When crossed with TCL1 Tg mice, Arid3a KO mice still showed no increased B1a cells in PBL during aging, and B CLL/lymphoma incidence did not occur, in contrast to Arid3a WT littermates." (PMID 30930899, 2019). "However, it confirmed that overexpression of Arid3a in adult BM directed MHC class II negative pre-B and immature cell generation similar to early neonatal liver, and Btk dependent B1a cells were continuously present, increased in aged, and capable of becoming CLL/lymphoma." (PMID 30930899, 2019).
osteosarcoma (2 papers, 2021 to 2025). A usually aggressive malignant bone-forming mesenchymal neoplasm, predominantly affecting adolescents and young adults. "miR-361-3p was also upregulated in osteosarcoma and facilitated tumorigenesis of osteosarcoma cells through regulating ARID3A." (PMID 40640983, 2025). "LncRNA E2F1-regulated Inhibitor of Cell Death (ERICD) can interact with AT-rich interaction domain 3A (ARID3A) via the E2F transcription factor 1 (E2F1) so as to regulate the proliferation and migration of osteosarcoma cells." (PMID 34373436, 2021).